SNORD42 (Small nucleolar RNA SNORD42 )
Synonyms: LOC124900890
Gene: Small nucleolar RNA gene on chromosome 4 (82,402,638 to 82,402,706, reverse strand). Ensembl gene ENSG00000202440.
Gene Ontology:
Biological process: RNA processing
Cellular component: nucleolus
Homologues: Orthologues: chimpanzee SNORD42 (100% identical), macaque SNORD42 (90% identical), zebrafish SNORD42 (65% identical), dog SNORD42 (62% identical). Paralogues in human: SNORD42B (86% identical), SNORD42 (72% identical), SNORD42A (58% identical).
Diseases named in the same sentence as SNORD42 in open-access papers:
SNORD42 is named in the same sentence as 1 disease in open-access papers, as found by Europe PMC text mining. Sharing a sentence is not in itself a finding about the gene and the disease.
SNORD42 shares sentences with these, for which no sentence is quoted: non-small cell lung carcinoma (1 paper).